TTC39C (tetratricopeptide repeat domain 39C)
Synonyms: C18orf17; FLJ33761; HsT2697
Tractability: PROTAC: ubiquitination databases record sites on it; its protein half-life has been measured.
Gene: Protein-coding gene on chromosome 18 (23,992,773 to 24,135,970, forward strand). Ensembl gene ENSG00000168234.
Subcellular location (Human Protein Atlas): Nucleoplasm
Gene Ontology:
Biological process: cilium assembly; otolith morphogenesis
Genetic constraint (gnomAD): Loss-of-function variants: 22 observed, 57.97 expected, observed/expected ratio (o/e) 0.38, 90% interval 0.27 to 0.54. The upper end of that interval is the gene's LOEUF score, 0.54, which puts it in group 2 of 6, group 1 being the genes least tolerant of losing a copy. Missense variants: 527 observed, 634.55 expected, observed/expected ratio (o/e) 0.83, 90% interval 0.77 to 0.89. Synonymous variants: 230 observed, 233.82 expected, observed/expected ratio (o/e) 0.98, 90% interval 0.88 to 1.1.
Homologues: Orthologues: chimpanzee TTC39C (99% identical), pig TTC39C (98% identical), dog TTC39C (98% identical), guinea pig TTC39C (97% identical), rat Ttc39c (94% identical), mouse Ttc39c (94% identical), macaque TTC39C (93% identical), rabbit TTC39C (89% identical), tropical clawed frog ttc39c (85% identical), zebrafish ttc39c (73% identical), Caenorhabditis elegans ttc-39B (21% identical). Paralogues in human: TTC39B (25% identical), TTC39A (23% identical).
Diseases named in the same sentence as TTC39C in open-access papers:
TTC39C is named in the same sentence as 4 diseases in open-access papers, as found by Europe PMC text mining. Sharing a sentence is not in itself a finding about the gene and the disease. The quoted sentences say what the papers report.
lung adenocarcinoma (1 paper, 2022). A carcinoma that arises from the lung and is characterized by the presence of malignant glandular epithelial cells. "To summarize, Ttc39c strongly regulates the proliferation and metastasis of lung adenocarcinoma cells." (PMID 36303158, 2022).
lung carcinoma (1 paper, 2022). "The proliferation, metastasis, and cloning ability of human lung cancer cells were inhibited, while the apoptosis of cells increased significantly after the depletion of Ttc39c." (PMID 36303158, 2022). "We also studied the function of Ttc39c in the lung cancer cells A549 and NCI-H1299." (PMID 36303158, 2022).
tumor (1 paper, 2022). "The mRNA and protein expression levels and the metabolites in tumor samples of the Ttc39c-knockout mice were measured comprehensively to elucidate the entire expression profile, which can be used to analyze the genes, proteins, and pathways regulated by Ttc39c." (PMID 36303158, 2022).
TTC39C also shares sentences with these, for which no sentence is quoted: cancer (1 paper).